ALB (albumin)
Diseases named in the same sentence as ALB in open-access papers (continued):
Sharing a sentence is not in itself a finding about the gene and the disease.
tumor (continued). "Functionalized albumin nanoparticles can target tumor organelles (nucleus or mitochondria) the same way as liposomes." (PMID 35203695, 2022). "The serum albumin (SA) serves as efficient drug delivery and tumor-targeted vehicle because it can conjugate or encapsulate chemotherapeutic agents." (PMID 35778747, 2022). "On the other hand, however, in our previous studies we showed that Zn-Pheide binds strongly to albumin, which significantly impairs its uptake by tumor cells, thus reducing it efficacy." (PMID 35215347, 2022). "The nomogram comprised baseline tumor LS and albumin-bilirubin grade (ALBI), which provided favorable calibration and discrimination in the training dataset with an AUC of 0.840 (95%CI: 0.750-0.931) and a C-index of 0.828." (PMID 35757765, 2022). "Some factors have been associated with poor outcomes, including tumor volume > 100 cm3, axial location, increased LDH levels, low serum albumin levels, metastasis, older age, and neural differentiation." (PMID 35354472, 2022). "Other than an inflammatory status with the production of cytokines activating phase acute, the tumor is characterized by a reduction of noble proteins (albumin, pre-albumin, transferrin)." (PMID 35756636, 2022). "Serum levels of PTH, albumin-corrected Ca, tumor size, eGFR, BMDs (all P<0.001), and clinical symptoms became milder in recent 10 years." (PMID 35784571, 2022). "Attributed to these passive and active tumor-targeting mechanisms, albumin has been considered a versatile cargo for anticancer agents." (PMID 35456562, 2022). "When the albumin level of the body decreases, these functions are weakened, and tumor progression is then promoted." (PMID 35086516, 2022). "Targeted delivery of anti-tumor drugs via albumin has shown anti-tumor potential in previous studies." (PMID 35416106, 2022). "The consistent covariables vital to the RFS included PS status, SUVmax, hemoglobin, PWR, ascites, BMI, albumin, presentation status, tumor size, age, completeness of surgery, pathological subtypes, and fibrinogen." (PMID 36387243, 2022). "The Okuda prediction model, one of the oldest staging systems, is a scoring scheme based on tumor size, ascites, serum bilirubin, and serum albumin levels; each scored 0/1." (PMID 35884412, 2022). "A link between albumin consumption by tumor cells and low FcRn expression has also been described in cancer cell proliferation." (PMID 36077002, 2022). "At the histological level, our data show some degree of tumor differentiation induced by 5-Aza, which was accompanied by an increase in mRNA levels of the differentiation marker albumin." (PMID 35406401, 2022). "sPLS‐DA showed primary and CRLM tumour compartments to be similar (classification error rate 40.5%), with ALB overexpression in the CRLM tumour compartment responsible for most of the discrimination between groups." (PMID 34874125, 2022). "Comparing laparoscopic and open groups, patients in the laparoscopic group had significantly lower BMI, higher albumin levels, and less T4 tumours." (PMID 35992209, 2022). "In 2019, Faroongsarng and colleagues described how tumor invasion through unusual metabolism results in significant changes of albumin stability." (PMID 36551631, 2022). "We show that pretreatment serum albumin is a broad and powerful predictor of both radiographic tumor response and patient prognosis following ICB treatment." (PMID 35393553, 2022). "There were no statistical differences in preoperative clinical parameters, including age, sex, BMI, tumor size, TBil, ALB, Hb, malignant tumor and benign tumor, among the OPD, LPD, and RPD groups." (PMID 36138358, 2022). "In those risk models, parameters such as pain, performance status, serum markers (PSA, hemoglobin, alkaline phosphatase, lactate dehydrogenase, and albumin), tumor grade, metastatic sites, and disease kinetics were utilized." (PMID 35229000, 2022).
tumor (continued). "Multivariate Cox analysis showed that the presence of TLSs, AST, lymph, ALB, tumour capsule, Child grade and BCLC stage were independent prognostic factors of RFS." (PMID 36291944, 2022). "Albumin has shown remarkable promise as a natural drug carrier by improving pharmacokinetic (PK) profiles of anticancer drugs for tumor-targeted delivery." (PMID 35456562, 2022). "Given that both GGT and albumin influenced tumour progression, some scholars combined them to evaluate the prognostic ability of them in tumors." (PMID 35481993, 2022). "In the present study, two major subsets of tumor cells, ALB + and ID3 + tumor cells were identified in iCCApps." (PMID 35347134, 2022). "Albumin nanosystems have unique properties of targeting tumor cells, due to their possibility of improving in vivo drug distribution and reducing drug toxicity." (PMID 35203695, 2022). "Among the 41 prognostic FRDEGs, all of them were upregulated in tumor tissue except ALB, which was visualized using a heatmap." (PMID 35938001, 2022). "An albumin-LDM conjugate previously constructed by our research group exhibited anti-tumor efficacy both in vitro and in vivo." (PMID 35416106, 2022). "Another phase I study is evaluating the safety and efficacy of these rapamycin-albumin nanoparticles in patients with stage III breast tumors among other tumor types (NCT02646319)." (PMID 35267507, 2022). "In multivariate analysis, modified albumin–bilirubin (mALBI) grade and up to seven criteria were identified as independent factors for OS, and mALBI grade and tumor morphology were identified as independent factors for PFS." (PMID 36291850, 2022). "The apparent larger size of the resulting complex of the targeting agent with albumin would reduce renal filtration and thus uptake, and albumin is documented to have good tumor exposure, which would allow retained tumor targeting." (PMID 36432709, 2022). "For example, albumin bound-MnO2 NPs increased tumor oxygenation by 45% by converting endogenous H2O2 in the tumor to oxygen." (PMID 35624636, 2022). "Albumin nanoparticles can enter tumor tissues by passive targeting, or cells via the EPR effect of tumor environment." (PMID 35126516, 2022). "These derivatives rapidly bind to Cys-34 of endogenous albumin in situ with acid-sensitive promoted or enzymatic release at the tumor site." (PMID 35745747, 2022). "Owing to the patient’s age and tumor location, systemic chemotherapy combined with immunotherapy was administered: intravenous infusion of albumin-paclitaxel 160 mg (D1, D8) combined with camrelizumab 200 mg (D1)." (PMID 36703957, 2022). "After intravenous administration, Al-ProD showed a significantly extended in vivo half-life than free DOX via binding with endogenous albumin, thereby increasing tumor accumulation." (PMID 35456562, 2022). "Lower BMI was associated with poorer nutritional and immunological status (such as having lower albumin concentration and lymphocyte count), lower hemoglobin level, more advanced tumor stage, and being less likely to receive PAC." (PMID 35769709, 2022). "No significant between-group differences were found for sex, BMI, ASA scores, preoperative hemoglobin and albumin levels, tumor characteristics, or medical history, such as abdominal surgery history." (PMID 36276133, 2022). "Nevertheless, binding of certain proteins, such as albumin, can allow nanoparticles to evade the immune system and can increase targeting to tumour cells." (PMID 36005826, 2022). "Serum albumin is predictive of tumor response to ICB in addition to being generally prognostic for survival." (PMID 35393553, 2022). "First, previous studies have shown that ALB is significantly inhibited during cancer‐related systemic inflammation, which is regulated by a variety of cytokines and growth factors produced by tumor cells and immune cells." (PMID 34997982, 2022).
tumor (continued). "For example, PTX-loaded albumin nanoparticles that were conjugated with anti-PD-L1 mAbs through a pH-sensitive linker showed enhanced tumor accumulation, effector T cell infiltration, and regulatory T cell suppression with low organ toxicity." (PMID 36015215, 2022). "Aldoxorubicin (aldoxo) is a prodrug of doxo that binds serum albumin through an integrated acid-sensitive linker, thereby increasing its half-life time and tumor specificity as the linker is mainly hydrolyzed in the acidic environment of the tumor." (PMID 35453612, 2022). "The ABD was introduced into this construct to reduce renal excretion of the targeted drug by binding to serum albumin and increasing its bioavailability and tumor accumulation." (PMID 35335898, 2022). "Albumin-based nanocarriers tend to accumulate in the tumor site through a specific transendothelial transport process, increasing the tumor-targeted delivery potential." (PMID 35954481, 2022). "As the usefulness of albumin in terms of its pharmacokinetic property and tumor specificity was demonstrated, considerable attempts have been made to develop albumin-based anticancer drug carriers." (PMID 35456562, 2022). "A recent study first reported that ALB acts as a tumour suppressor and plays a vital role in HCC progression, particularly in invasion and metastasis." (PMID 36132141, 2022). "These were the AFP, albumin, tumor diameter, vascular invasion, PLR, RDW-CV, and RDW-SD, respectively." (PMID 36005195, 2022). "This concept led to the proposal of the CRP-to-albumin ratio (CAR) as a tool for assessing the extent of inflammation in a tumor microenvironment and, consequently, predicting prognosis." (PMID 35562926, 2022). "A newly invented PRE-Stage was developed using a CRP–albumin–lymphocyte index < 3, central tumor location, and CA19-9 level > 40 U/mL, and it was able to significantly predict DSS and DFS when the patients were stratified into four stages (p < 0.05)." (PMID 35267414, 2022). "Tumour cells can inhibit the liver’s ability to synthesise albumin by releasing inflammatory cytokines and/or promoting invasion and metastasis." (PMID 36614896, 2022). "Here, this work reports solvothermally synthesized photoactivatable Pt(IV)‐coordinated carbon dots (Pt‐CDs) and their bovine serum albumin (BSA) complex (Pt‐CDs@BSA) as a novel orange light‐triggered anti‐tumor therapeutic agent." (PMID 36307905, 2022). "With extended in vivo circulation, EMC-DEVD-S-DOX bound to endogenous albumin efficiently accumulated within the tumor tissues with a detectable amount of the substances for more than 120 h." (PMID 35456562, 2022). "The bioavailability of albumin-bound paclitaxel (Abraxane) in the tumor is facilitated by the gp60 receptor (albondin)-mediated pathway in the endothelial cell walls of tumors, which binds to albumin with a high affinity." (PMID 35057002, 2022). "Only two genes were found to be differentially expressed between case primary and paired CRLM tumours; albumin (ALB) and collagen type IV alpha 2 chain (COL4A2)." (PMID 34874125, 2022). "Serum albumin is a candidate biomarker that can be combined with tumor mutational burden (TMB) for additional predictive capacity, and the tumor response rate to ICB was ~49% in the albumin-high/TMB-high group." (PMID 35393553, 2022). "In summary, the platelet-based and platelet-mimicking human serum albumin submicron particles offered a promising approach for metastatic cancer therapy and tracking through accurate targeting for tumor cells." (PMID 36430755, 2022). "Among albumins, human serum albumin (HSA) and bovine serum albumin (BSA) are more suitable candidates for transporting or carrying drugs to the target site in tumor therapy." (PMID 35456577, 2022). "In this study, albumin binders were used to increase tumor uptake for therapeutic applications while the non-albumin peptide was evaluated as a potential positron emission tomography (PET) imaging agent." (PMID 35215341, 2022).
tumor (continued). "Both albumin binders and their derivatives have been utilized for lymph node, tumor, and blood pool imaging due to their improved pharmacokinetics." (PMID 35215341, 2022). "The progressive tumor invasion can lead to malnutrition, and the host’s response to the tumor can also lead to some changes in albumin levels." (PMID 35198443, 2022). "The rapid proliferation of tumor cells often requires excessive nutrients, including albumin, folic acid, and iron." (PMID 36678653, 2022). "This work included altogether 216 patients with complete data, such as age, sex, tumor grade, T-stage, clinical stage, albumin level, platelet level, AFP level, and vascular invasion from the TCGA-HCC cohort." (PMID 36267406, 2022). "The most commonly used predictors were AFP (n = 9), albumin (n = 8), bilirubin (n = 8), Child–Pugh class (n = 8), extrahepatic metastasis (n = 7), tumor size (n = 7), and vascular invasion (n = 6)." (PMID 35810271, 2022). "Albumin also binds to several other surface receptors highly expressed in tumor and inflammatory environments, including the glioblastoma-expressed protein SPARC (secreted protein acidic and rich in cysteine)." (PMID 36365214, 2022). "It suggested these aptamers modified with F bases bind to albumin and form a stable complex compared with the imaging result of Sgc8, and they also displayed targeted releasing to tumor cells from the binding with albumin." (PMID 35293579, 2022). "Albumin was recently shown to play a tumor suppressor role in HCC by suppressing migration and invasion in HCC cell lines." (PMID 35406456, 2022). "For example, lesions with different degrees of malignancy would have different MID:BSA uptakes, as the uptake of extracellular proteins such as serum albumin is markedly activated in rapidly growing tumor cells." (PMID 35888170, 2022). "TS binds to serum albumin immediately after intravenous injection and is distributed to the tumor cells through the disrupted blood–brain barrier." (PMID 36505805, 2022). "The cells in clusters 3, 4, 6, 7, 10, 15, 23, 25, 26, and 35 originated from tumor specimens and were highly expressed in ALB, KRT18, and CD24; therefore, they were labeled as malignant cells." (PMID 36605219, 2022). "P1, which constituted a major fraction of HB tumor cells and had the highest C1 group score, exhibited a more mature hepatocyte-like phenotype, expressing the highest level of ALB as well as liver metabolism genes (e.g., CYP2E1, GSTA1, G6PC)." (PMID 35860547, 2022). "We further compared the CEA and Albumin level between tumor stage III and IV and noticed that the CEA level was significantly higher in stage IV than stage III (124.9 vs 7.66, p = 007)." (PMID 35395754, 2022). "Here, we detected a group of ALB-expressing tumor cells at the single-cell level, most of which (79.4%) were present in the S100P-SPP1 + iCCApps." (PMID 35347134, 2022). "Here, we chose afatinib as second-line therapy, in conjunction with albumin–paclitaxel chemotherapy, leading to stabilized tumor progression with good tolerance of this case." (PMID 36703957, 2022). "ORs (95%CIs) for upper 3rd serum PTH, albumin-corrected calcium levels and tumor size in PHPT patients with famine exposure at different stages of life." (PMID 35784571, 2022). "For example, nano-albumin-bound (Nab)-paclitaxel, a nano-based drug commonly used in PDAC treatment, was proven to deplete the tumor stroma through the interaction between the albumin and secreted protein acid, and is rich in cysteine." (PMID 36297467, 2022). "We fused B9 to albumin-bindingdomains with varying affinity (ABDlow and ABDhigh), to assess the effect on the pharmacokineticsof the tracer and tumor uptake." (PMID 35044182, 2022). "Multivariate Cox model identified depth of invasion, lymph node invasion, tumor differentiation, adjuvant chemotherapy, CA724, and platelet-albumin ratio as covariates associated with CSS and DFS." (PMID 36386541, 2022).
tumor (continued). "Multivariate analyses identified large tumor size on CT (odds ratio [OR], 1.07; P = .041), high albumin level (OR, 10.6; P < .001), SVR (OR, 25.9; P = .004), and SAL (OR, 19.6; P = .009) were risk factors for variceal formation at postoperative 3 mo." (PMID 35634189, 2022). "Albumin nanoparticles accumulate in tumor tissue both through passive and active targeting, and therefore, albumin nanoparticles have a high therapeutic potential." (PMID 35563426, 2022). "ALB is a tumor suppressor in HCC that can inhibit the proliferation of HCC cells and regulate the cell cycle." (PMID 36275701, 2022). "Albumin-bound nanoparticles (nabTM) have been widely used for tumor treatment due to elevated albumin accumulation within tumors." (PMID 36153528, 2022). "Although albumin expression was lower in tumour isolates than in tumour-free isolates (p = 0.02), isolated albumin-positive hepatocytes expressed HLA-I to a similar degree across tumour and tumour-free samples (p = 0.38)." (PMID 36185575, 2022). "Three clinical variables were controlled in multivariate analysis: preoperative albumin level, primary tumor growth, and metastasis location." (PMID 35262530, 2022). "Patients who underwent conversion therapy had higher serum albumin levels and a trend toward a smaller main tumor size, SN type, and lower serum AFP levels." (PMID 36291850, 2022). "The PROSASH-II model, which comprised albumin, bilirubin, vascular invasion, extrahepatic spread, tumor size and AFP, has been shown to have good discriminative value in predicting the survival of patients with HCC receiving sorafenib treatment." (PMID 35454919, 2022). "We then constructed a prognostic model integrating albumin-bilirubin grade, tumor size, macrovascular invasion, and TINCR expression, and HCC patients were divided into low, intermediate, and high-risk groups (Table." (PMID 34980201, 2022). "This system showed intriguing results in vivo: the biomimetic albumin coating brought a 2.5 times improvement in tumor accumulation and considerably improved deep penetration ability in tumors compared with the non-coating group." (PMID 36134930, 2022). "Moreover, as a component of systemic inflammation, ALB is correlated with cancer-related systemic inflammation and tumor progression, which may be caused by the reduced production of ALB by hepatocytes due to the inflammatory cytokines released by the tumor cells." (PMID 35967813, 2022). "In this study, patients in the LW group had significantly lower serum albumin concentrations, greater tumor depth, and more advanced lymph node metastases." (PMID 35932031, 2022). "This time period is more clinically relevant than that identified in the binary poor prognosis groups for NC or albumin alone, being shorter than the 12 weeks at which a first radiological tumour assessment is typically carried out." (PMID 35398717, 2022). "A colloidal suspension of albumin-paclitaxel nanoparticles (nab-paclitaxel) created for the purpose of increasing paclitaxel permeation through tumour albumin receptors proved to be 4.5 times more effective compared to conventional PTX." (PMID 36555256, 2022). "Several attempts focused on the derivatization of radioligands with 4-(p-iodophenyl)butanoate or Evans blue as strong albumin binders to enhance the radioligands’ blood circulation time and, hence, achieve increased tumor accumulation." (PMID 35635566, 2022). "Further analysis on pharmacokinetics and biodistribution in vivo added that Cim-F-alb exhibited prolonged circulation time and higher tumor accumulation than Abraxane®, and less interaction with serum proteins were ascribed to albumin coating." (PMID 35456631, 2022). "Consistently, the albumin-modified gold nanoparticles showed significantly enhanced antitumor efficacy with high tumor accumulation." (PMID 35456562, 2022).